APC (APC regulator of Wnt signaling pathway)
Diseases named in the same sentence as APC in open-access papers (continued):
Sharing a sentence is not in itself a finding about the gene and the disease.
cancer (continued). "However, no consistent upregulation was observed in mRNA expression of these junction proteins in APC-mutated cancers, suggesting a more complex regulation with inputs from other transcription cascades possibly contributing to the final mRNA output." (PMID 37998722, 2023). "Despite decades of research, safe drugs that correct APC loss in (colon) cancer remain elusive." (PMID 36669491, 2023). "Moreover, since most Wnt-associated cancers carry APC mutations, enhancing the destruction complex’s function is impossible." (PMID 37190019, 2023). "Moreover, these strategies cannot be effective for most Wnt-mutated cancers that carry APC or CTNNB1 mutations downstream of Wnt ligands and receptors." (PMID 37190019, 2023). "There is also a link between cancer and mutations in the APC gene." (PMID 37901797, 2023). "Among the younger group, 53 had BRCA1/2 germline PVs/LPVs (38%), 15 were carriers of other cancer susceptibility genes (10%), primarily APC, NBN, ATM, MUTYH, MLH1, and only 2 patients were carriers of PVs/LPVs in both BRCA1/2 and other susceptibility genes (1%)." (PMID 38136276, 2023). "As a result of APC mutation, energy metabolic pathways may change, which also aids in cancer growth." (PMID 36879264, 2023). "Clusters of TCF4 binding sites are present in promoters of the CLDN2, CLDN4, CLDN7, and OCLN genes, and these genes could thus be upregulated in cancers with APC mutations." (PMID 37998722, 2023). "We also suggest the hypothesis that alternative splicing caused by the APC loss of function could contribute to the malignant phenotypes associated with APC-related cancers." (PMID 37489330, 2023). "Interestingly, truncation mutations in the APC/C subunit CDC27 are frequently found in cancer, and cell lines engineered with these mutations display elongated mitotic timing and reduction of CIN." (PMID 36859339, 2023). "We discovered an effective APC mutation in two cancer cohorts." (PMID 36204371, 2022). "Depending on the type of cancer, the Wnt pathway can be upregulated by different mechanisms, including the overexpression of specific components, epigenetic dysregulation (e.g., APC promoter hypermethylation), somatic mutations or gene fusions." (PMID 35327645, 2022). "In other cancer types, APC mutations are associated with either reduced or increased survival." (PMID 35327645, 2022). "Significantly, this study elucidates a novel synthetic lethal interaction between APC mutation and statin treatment, which could potentially be exploited for the treatment of a specific subset of APC mutated cancers." (PMID 35712511, 2022). "Interestingly, the metastatic cancer cells acquired additional mutations in Wnt pathway components (APC mutations or amplifications of LRP6 and WNT2B), underlining the importance of Wnt signaling for metastasis." (PMID 35327645, 2022). "Moreover, it was previously revealed that during cancer initiation, a high mutation level was detected in the APC gene." (PMID 35723313, 2022). "The induction of the complex upon APC mutation (Wnt‐up) increases TRα1 expression in cancers." (PMID 36217307, 2022). "To assess the performance of this screening platform, we began with β-catenin, a key hub in the Wnt signaling pathway that is an attractive intracellular target for therapeutic intervention in the many Wnt-driven cancers, such as those with APC or CTNNB1 mutations." (PMID 36534810, 2022). "We sought to clarify the role and the underlying molecular mechanism of APC in various cancers." (PMID 35303016, 2022).
cancer (continued). "We support a standard D2 gastrectomy in patients with a family history, typical endoscopic findings and verified mutations in the adenomatous polyposis coli (APC) promoter genes as early cancer may be overlooked by endoscopic surveillance." (PMID 35397558, 2022). "Thus, degeneration of the c-Myc protein due to APC mutations in the progression from AD to cancer in the AD–carcinoma sequence is supported by the metabolomic findings of this study." (PMID 35050180, 2022). "We, therefore, must assume that APC/CTNNB1 somatic mutations may have differential effects in cancer cells other than by merely activating β-catenin." (PMID 34986841, 2022). "Similarly, disrupting the localization of APC‐dependent mRNAs as a group, or perturbing the localization of individual transcripts, causes defects in cell migration, cancer cell invasion and blood vessel morphogenesis." (PMID 35166036, 2022). "Significantly, we have identified a novel synthetic lethal dependence between APC mutations and statin treatment, which could potentially be exploited for the treatment of APC mutated cancers." (PMID 35712511, 2022). "Additionally, the declined APC protein expression caused chromosomal instability, mutation, and cancer." (PMID 35910834, 2022). "Interestingly, ATM, a moderate-penetrance cancer susceptible gene, and APC genes were previously reported as key components showing potential for targeted therapy." (PMID 36672847, 2022). "In CRC histogenesis, the role of the SRIF system (mainly SST and SST1) is linked to APC gene mutations and could involve dysregulation of feedback mechanisms between cancer stem cells and neuroendocrine cells present in the niches of intestinal crypts." (PMID 34829972, 2021). "In contrast, the other three generic disordered drivers are predominantly altered via localized mutations in their disordered regions: the degrons of β-catenin and NRF2 and the central region of APC, and hence these are true disordered drivers which are commonly mutated in several cancer types." (PMID 33806614, 2021). "This cancer starts off with an adenomatous polyp in the epithelial cells of the colon or rectum, which arises due to mutations in the tumour suppressor gene adenomatous polyposis coli (APC)." (PMID 33807355, 2021). "In addition to pathogenic variants, we identified 9 variants of uncertain significance (VUS) in 7 genes and 1 novel missense variant in the APC gene in additional 10 cancer patients." (PMID 35070997, 2021). "In addition, tier II variants were detected in another 27 cancer-relevant genes, including APC, which was the gene with the most tier II variants identified." (PMID 34640513, 2021). "The seemingly lower effect of APC mutations in double-targeted tumors is interesting in light of the reported difference in prognostic associations of single and double-targeted MSS CRCs, although the single-mutated group had improved survival compared to double-mutated and APC wild-type cancers." (PMID 34470667, 2021). "The adenomatous polyposis coli (APC) is a frequently mutated tumour suppressor gene in cancers." (PMID 34155197, 2021). "Moreover, complete loss of APC function is rarely found even in cancer cells which harbor APC mutations." (PMID 34552058, 2021). "However, the Cancer Hotspot Panel 2.0 was used in their study, which detects only hot spot mutations of APC gene." (PMID 33854094, 2021). "Loss of varying numbers of these motifs by APC truncating mutations within the intestinal stem cell compartment confers high basal β-catenin levels and initiates up to 80% of colorectal cancers (CRCs), the third most common cancer type worldwide." (PMID 34352208, 2021).
cancer (continued). "Moreover, treatment of CRC organoids with metformin—an anti-cancer drug—has shown a significant anti-cancer effect, especially in the early stages when APC mutations are reported." (PMID 34571724, 2021). "Ten out of 17 incident cancers presented with a total of 14 truncating APC mutations." (PMID 34206061, 2021). "Thus we were able to demonstrate that C2 had inhibitory effect on the growth of cancer-initiating cells driven by APC mutation." (PMID 32415084, 2020). "However, the present study has confirmed that a minority of BRAF mutant cancers do carry a truncating APC mutation." (PMID 32384699, 2020). "APC is lost in numerous cancer types, through either mutations or promoter hypermethylation." (PMID 33105836, 2020). "In the context of cancers too, the role of Wnt-β-catenin has been widely and extensively studied as mutations in β-catenin and in its hallmark regulators APC and Axin promote deregulated cell proliferation and are now considered oncogenes in a wide array of contexts." (PMID 31974352, 2020). "Besides CRC, APC mutation is also associated with the genesis of other types of cancers, such as gastric cancer and hepatoblastoma." (PMID 32824859, 2020). "There is evidence that even major and/or cancer-initiating driver mutations (e.g. APC, IDH1/2, KRAS, PIK3CA, etc.)are differentially selected depending on cancer type, strongly suggesting a role for the TME, broadly defined, in selecting many of the common driver mutations." (PMID 32289242, 2020). "Moreover, our data showed that loss of APC function from promoter methylation status is trends to be aggressive behavior of cancer cell." (PMID 33369461, 2020). "The average age of BRAF mutant cancers harboring APC mutation was 12 years less than APC wild-type." (PMID 32384699, 2020). "Indeed, Tankyrase inhibitors have been shown to negatively regulate Wnt signaling in APC-mutated cancer cells." (PMID 32037398, 2020). "Elegant work in both murine models of intestinal neoplasia and human cancer cell lines has highlighted the critical role for the oncoprotein MYC as an essential downstream driver of Wnt/β-catenin driven oncogenicity followed by APC loss." (PMID 32961708, 2020). "Detailed studies are required to determine how loss of MACROD2 might cooperate with loss of APC to drive cancer." (PMID 32151005, 2020). "Interestingly, loss of RAD52 has been shown to reduces cancer predisposition and increases the lifespan of adenomatous polyposis coli (APC)- or ataxia-telangiectasia mutated (ATM)-deficient animals." (PMID 32355220, 2020). "We investigated whether the loss of APC alters the response of colonic epithelial cells to infection by Salmonella enterica, the only genotoxin‐producing bacterium associated with cancer in humans." (PMID 31414579, 2019). "Most cancer-related mutations in APC occur within the Mutation Cluster Region (MCR) of APC that produces a N-terminal trunctated protein (~150 KDa, instead of the full-length 310 KDa protein) which is unable to bind β-catenin and mark it for ubiquitination and subsequent proteasomal degradation." (PMID 30828563, 2019). "MMP-7 activation is directly associated with APC, and it is well established that APC mutations are frequently implicated as among the first mutations that occurs in the disease history of colon polyps as they progress to cancer." (PMID 31200666, 2019). "In addition, intestinal barrier dysfunction promotes bacterial invasion, sustains intestinal inflammation, and eventually results in mutations in the adenomatous polyposis coli (APC) gene and carcinoma development." (PMID 31860645, 2019). "Importantly, we also show that inhibition of Cdc20 promotes mitotic cell death more effectively than loss of APC/C activity through differential effects on Mcl‐1 degradation, providing an improved strategy to kill cancer cells." (PMID 29987118, 2018).
cancer (continued). "In contrast, somatic APC gene mutations arising as second hits during polyp development could serve as potentially targetable sources for cancer vaccines, if proven to be immunogenic." (PMID 30256815, 2018). "Alternatively, healthy cGMP tone may promote a homeostatic microenvironment that suppresses proliferative signaling, inflammation, and desmoplasia, thereby preventing cancer progression in spite of APC/β-catenin mutations." (PMID 30131940, 2018). "Importantly, the inhibition of Wnt signaling occurred downstream of β-catenin, encouraging applications in treatment of cancers caused by APC and β-catenin mutations." (PMID 29977599, 2018). "Five of the inherited variants in genes associated with cancer or actionable for hereditary diseases have been described in the literature as pathogenic (MUTYH: c.933+3A > C) or of unknown significance (APC, APOB, DSG2, DSP)." (PMID 30233642, 2018). "Under conditional loss of the APC gene, Krt9+ cells display cancer-initiating abilities." (PMID 29652830, 2018). "Furthermore, loss of heterozygosity (LOH) of APC has been shown to be one of the earliest and rate-limiting events in the progression from normal epithelium to adenoma formation and then cancer." (PMID 30024920, 2018). "The BRAF mutant serrated pathway rarely mutates APC in this manner; however, activation of the Wnt pathway can occur through alternative mechanisms as nuclear beta-catenin is evident in approximately half of the serrated dysplastic polyps and cancers studied." (PMID 30598662, 2018). "The hyperexpression of WNT target genes corresponds with the hyperactivated WNT pathway in primary CRC and CRC cancer cell lines, most likely resulting from the biallelic inactivation mutation of APC, FBXW7, AXIN2, and FAM123B or the activating mutations in CTNNB1." (PMID 30363662, 2018). "Upon experimental validation, many of these predicted immunogenic peptides could qualify as cancer vaccine candidates that could be used along with adoptive T-cell therapy to treat patients harboring specific APC somatic gene mutations." (PMID 30256815, 2018). "Among the filtered variants listed, we searched for the genes that were catalogued in the COSMIC cancer Gene Census as known germline mutations predisposing to cancers and identified a heterozygous APC missense mutation c.A136G (p.T46A), which was further validated with Sanger sequencing." (PMID 29190888, 2017). "In addition, a mutation of APC must be followed by other mutations in some genes such as other TSGs to develop into cancer." (PMID 28331559, 2017). "This screen was performed because APC plays a pivotal role in this kind of cancer: the majority of CRC tumors are initiated by mutation or loss of function of both APC alleles in normal colon cells, which results in the formation of a precancerous lesion that can eventually progress to carcinoma." (PMID 28561751, 2017). "As less doubling time implies faster proliferation rate, the mutation of APC or KRAS may lead to enhanced malignancy of cancers." (PMID 26937901, 2016). "Adenomatous polyposis coli (APC) protein (2843 aa) is a large multi-domain protein encoded by the tumor suppressor APC gene, and is involved in the Wnt signaling pathway that plays an integral role in cell adhesion and proliferation in cancer." (PMID 27218803, 2016). "When cancer was compared to normal controls, subgroup analysis of ethnicity showed that the pooled OR from the Asian and Caucasian populations was similar, suggesting that Asian and Caucasian populations were susceptible to APC promoter hypermethylation." (PMID 27670526, 2016).
cancer (continued). "We hypothesized that in serrated pathway cancers where APC mutation is uncommon, inactivation of RNF43 and/or ZNRF3 would present an alternate mechanism for activating the Wnt signal." (PMID 27661107, 2016). "These subtypes are independent from APC germline mutation status, and the both subtypes could develop malignant tumors." (PMID 27563825, 2016). "Intense nuclear APC staining was noted in 65 tumors (53.3%), and this staining pattern was associated with a significantly (log-rank test; p = 0.015) worse cancer-specific survival rate (57% at 5 years) compared with tumors with only mild or medium staining intensity (68% at 5 years)." (PMID 27577083, 2016). "We reported that mutations in some cancer driver genes mutations in some cancer driver genes such as APC, KRAS, or PIK3CA might correlate with cancer proliferation or drug resistance." (PMID 26937901, 2016). "These subtypes might be formed independently from APC germline mutation status, and both subtypes could develop malignant tumors." (PMID 27563825, 2016). "Since negative regulators such as APC are frequently mutated in cancer, suppressor mutations and the mechanisms through which the affected genes regulate signaling may reveal therapeutic targets." (PMID 27996937, 2016). "Consequently, APC deficiency impairs the PTX sensitivity of cancer cells by interfering with the mitotic spindle checkpoint and decreasing apoptosis." (PMID 26900348, 2016). "However, they are more akin to carcinoma in terms of loss of adenomatous polyposis coli (APC) immunoreactivity, parafibromin expression, and gain of chromosome 5." (PMID 27756436, 2016). "The APC gene harbors the most number of somatic mutations in our study; although the frequency of APC mutations is around 30%, which is lower than previous studies on European populations, the results nevertheless confirmed that somatic mutation in APC is a key cancer driver for CRC." (PMID 25617745, 2015). "The data presented here, together with the ‘just-right’ signalling model for the role of APC mutations and β-catenin activity in cancer clearly show that β-catenin signalling is not a binary process and suggest additional levels of control of the β-catenin transcriptional output." (PMID 25647637, 2015). "Exploration of recurrent alterations in the branches of carcinoma-specific mutations with distinct mutational contexts such as ERBB2 amplification preceding APC and KRAS mutations would also be valuable information for understanding the evolutionary process of CRC." (PMID 26336987, 2015). "In cancers with mutated Axin or APC, the upstream antagonists acting on Wnts or their receptors may be less effective." (PMID 26056595, 2014). "Loss-of-function of APC mutations is common in many cancers." (PMID 25566502, 2014). "Furthermore cross-talk between RAS and BRAF oncogenes with other mutated pathways like PI3K and APC will provide new molecular mechanisms and will assist the design of efficient rational combinatorial anti-cancer protocols for personalised therapy." (PMID 25361007, 2014). "Cells with APC gene mutations may have a reduced ability to repair the damage from ionizing radiation, thus contributing to cancer predisposition." (PMID 26425572, 2013). "Therefore APC-NT antibodies can be used to purify endogenous APC proteins, both wild-type and cancer mutated, truncated APC." (PMID 24156781, 2013).